CTLA4 (cytotoxic T-lymphocyte associated protein 4)
Diseases named in the same sentence as CTLA4 in open-access papers (continued):
Sharing a sentence is not in itself a finding about the gene and the disease.
tumor (7,952 papers, 2006 to 2026). "Intravenous administration of anti-CTLA4 with anti-PD1 provides durable tumour responses but causes severe treatment-related adverse events in patients with cancer." (PMID 42056527, 2026). "In the intercellular correlation analysis of gene expression, tumor epithelial cell CEBPB expression was significantly correlated with cytotoxic T-lymphocyte associated protein 4 (CTLA4) expression in T cells, especially in regulatory and exhausted T cells." (PMID 41743630, 2026). "The crucial role of these molecules in tumor immune evasion has led to the development of anti-programmed cell death protein 1 (PD-1) and anti-cytotoxic T-lymphocyte-associated protein 4 (CTLA-4) therapies for cancer." (PMID 41596489, 2026). "For patients with tumor PD-L1 = 0%, there is a moderate benefit of dual checkpoint blockade with anti-cytotoxic T-lymphocyte-associated protein 4 plus anti-PD-1 combined with chemotherapy over standard anti-PD-1 plus chemotherapy." (PMID 41491099, 2026). "Tumor cells frequently exploit these inhibitory pathways to escape immune surveillance, among which the cytotoxic T-lymphocyte-associated antigen 4 (CTLA-4) and programmed cell death protein 1 (PD-1) pathways are the most representative." (PMID 41601655, 2026). "Emerging evidence suggests that a high burden of copy number loss is correlated with resistance to anti-PD-1 and anti-CTLA-4 therapies, indicating that copy number loss is closely linked to tumor immune evasion." (PMID 41584042, 2026). "For example, tumor cells can express immune checkpoint modulators like cytotoxic T-lymphocyte-associated protein 4 (CTLA-4) and programmed cell death ligand 1 (PD-L1), which act to suppress the immune response." (PMID 41550509, 2026). "We highlight two complementary immune activation strategies: tumor microenvironment remodeling via tyrosine kinase inhibitor-mediated vascular normalization, and intensified immune priming through cytotoxic T-lymphocyte-associated protein 4 blockade." (PMID 41909713, 2026). "Immune checkpoints that mediate tumor immune escape mainly include Programmed cell death protein 1 (PD-1), Programmed death-ligand 1 (PD-L1), and Cytotoxic T lymphocyte-associated antigen 4 (CTLA-4)." (PMID 40296912, 2025). "For instance, the expression of cytotoxic T-lymphocyte-associated antigen 4 (CTLA-4) on the surface of a tumor cell results in the inhibition of the cytotoxic activity of T-cells." (PMID 40821768, 2025). "Tregs, tumor-associated macrophages, and myeloid-derived suppressor cells inhibit T-cell activity via PD-1/PD-L1 and CTLA-4/CD80/86 pathways, while OSCC cells release VEGF, TGFβ, IL-6, and IL-10 to suppress immunity." (PMID 40924302, 2025). "Immune checkpoint inhibitors, such as programmed cell death protein 1 (PD-1) and cytotoxic T-lymphocyte-associated protein 4 (CTLA-4) inhibitors, can unleash T-cell-mediated cytotoxicity against BCSCs, thereby impeding tumor progression." (PMID 40191717, 2025). "Antibodies targeting immune checkpoints such as the programmed death-1 (PD-1) receptor, its ligand PD-L1, or cytotoxic T lymphocyte-associated-4 (CTLA-4) have transformed the treatment of many tumor types." (PMID 40948781, 2025). "Immune-targeted therapies break the cancer immune tolerance, restoring T-cell recognition against tumor cells and restraining the cytotoxic T-lymphocyte-associated antigen 4 (CTLA-4) and the programmed cell death 1 (PD-1)/ligand 1 (PD-L1) pathways." (PMID 40227797, 2025). "These pathways are conserved in dogs, with increased CTLA-4 or PD-L1 expression observed in tumor-infiltrating lymphocytes and associated with poor prognosis in malignant canine tumors." (PMID 40725420, 2025). "Tumor-infiltrating Treg cells exhibit increased expression of surface molecules like CTLA-4, which are associated with T cell activation suppression." (PMID 40136375, 2025).
tumor (continued). "Cytotoxic T lymphocyte-associated protein-4 (CTLA-4) is a protein expressed on the surface of T-cells that acts as protein that controls the bodies response to adverse cellular changes such as neoplasia." (PMID 39857950, 2025). "Immune checkpoint genes (e.g., PDCD1 and CTLA4) are often closely associated with immune escape mechanisms, as tumor cells express immune checkpoint molecules to suppress immune system attacks, thereby evading host immune surveillance." (PMID 40331946, 2025). "Immunotherapy has emerged as a promising strategy through the blockade of immune checkpoints, such as CTLA-4 and PD-1, which can rebalance the Immunoediting due to immunogenic mutations in favour of tumour elimination." (PMID 40831927, 2025). "ICIs targeting CTLA4 effectively enhance immunity, activate T cells, induce immunological memory, as well as upregulate the T cell response to tumor-associated neoantigens to kill cancer cells and attack Treg cells in tumors." (PMID 40584631, 2025). "By targeting cytotoxic T-lymphocyte-associated protein 4 (CTLA-4), programmed cell death protein 1 (PD-1), and programmed death-ligand 1 (PD-L1), immune checkpoint drugs have shown efficacy against various tumor types." (PMID 40426987, 2025). "Immune checkpoint molecules like PD-1 (programmed death-1) and CTLA-4 (Cytotoxic T lymphocyte-associated antigen-4) function as negative regulators of immune activation, and when triggered by tumor or tumor-associated cells, they suppress immune responses." (PMID 41179661, 2025). "Immune checkpoint inhibitors, especially programmed cell death protein 1 (PD-1), programmed cell death ligand 1 (PD-L1), and cytotoxic T-lymphocyte-associated protein 4 (CTLA-4), target the escape mechanisms of tumor cells." (PMID 39995679, 2025). "While most mRNA-based tumor vaccine studies in the literature focus exclusively on the administration of mRNA encoding tumor antigens, this study additionally used siRNA targeting CTLA-4, one of the major immunosuppressive mechanisms." (PMID 40943370, 2025). "Sustained low levels of IFN-γ increase the expression of molecules involved in tumor immune evasion, including programmed death-1 ligand 1 (PD-L1) and 2 (PD-L2) and cytotoxic T-lymphocyte-associated protein-4 (CTLA-4)." (PMID 40108693, 2025). "Both the hot and mutationally active subtypes exhibit high mutational burdens, more tumor-infiltrating lymphocytes (TILs), and peritumoral lymphocytes, along with upregulated immune checkpoints (CTLA-4 and PDL-1) and regulatory T cells." (PMID 40264765, 2025). "As an emerging tumor immunotherapy, the US Food and Drug Association has approved multiple immune checkpoint inhibitors, such as anti CTLA-4 antibodies and PD-1/PD-L1 inhibitors for clinical use." (PMID 41142609, 2025). "In 2011, an antibody targeting cytotoxic T lymphocyte-associated protein 4 (CTLA-4) on T cells opened up a new window for tumor treatment." (PMID 41463240, 2025). "ICIs targeting checkpoint proteins such as programmed cell death protein 1 (PD-1), programmed death-ligand 1 (PD-L1), and cytotoxic T-lymphocyte-associated protein-4 (CTLA-4) have demonstrated anti-tumor response in HCC." (PMID 40076561, 2025). "Immune checkpoint proteins, including cytotoxic T lymphocyte-associated molecule-4 (CTLA-4) and programmed cell death ligand-1 (PD-L1) which are able to cause T cells with tumor-killing inactivation and promotion of cancer cell growth and invasion." (PMID 40017598, 2025). "Similar strategies include HSV-1 oncr-177, which induces lasting anti-tumor immune memory in various immune active tumor models by encoding anti-PD-1 and anti-CTLA-4 single chain variable region fragments." (PMID 41425703, 2025). "When Tregs accumulate in the immune TME, they transmit inhibitory signals by expressing cytotoxic T lymphocyte-associated protein-4 (CTLA-4), thereby preventing DCs from presenting tumor antigens to CTLs, prompting immunosuppression." (PMID 40013141, 2025).
tumor (continued). "Other immune checkpoint blocking antibodies also elicit anti-tumor activity, exemplified by anti-cytotoxic T-lymphocyte associated protein 4 (CTLA-4), which is less widely used due to its toxic side effects." (PMID 40421087, 2025). "Immune checkpoint blockade, which involves targeting molecules such as programmed death-1 (PD-1)/PD-L1 and cytotoxic T-lymphocyte-associated antigen 4 (CTLA-4), can restore T cell function and reactivate anti-tumor immune responses." (PMID 41142435, 2025). "Treatment strategies represented by ICIs activate the body’s anti-tumor immune response by targeting key pathways such as PD-1(Programmed Cell Death Protein 1), PD-L1, and CTLA-4(Cytotoxic T-Lymphocyte Associated Protein 4)." (PMID 40963868, 2025). "Loss of MNX1 enhances T cell anti‐tumor immunity and cytotoxic T‐lymphocyte‐associated protein 4 (CTLA‐4) blockade therapy, providing a potential strategy for cancer immunotherapy." (PMID 39912421, 2025). "Depletion of MNX1 stimulates the cytotoxic T cell‐mediated anti‐tumor immunity and enhances the therapy effect of cytotoxic T‐lymphocyte‐associated protein 4 (CTLA‐4) blockade." (PMID 39912421, 2025). "Japanese researchers confirmed that cytotoxic T lymphocyte-associated antigen-4 (CTLA-4) is highly expressed in SPP1+ macrophages at the tumor invasion front, which are considered to be markers of exhaustion." (PMID 40191203, 2025). "ICIs target cytotoxic T-lymphocyte-associated antigen-4 (CTLA-4) or programmed cell death-1 (PD-1)/programmed cell death-ligand 1 (PD-L1) pathways to disrupt tumor immune evasion." (PMID 40881122, 2025). "A study of 112 HCC cases demonstrated that the quantity of CTLA-4+ on TILs correlated with high-grade tumors (Edmondson–Steiner grade III/IV), while CTLA-4 expression in tumor cells was linked to multiple lesions and lower tumor grades." (PMID 40941632, 2025). "Another ICI protein, anti-Cytotoxic T Lymphocyte associated Antigen-4 (CTLA-4) induces a stronger memory response than anti-PD-1 in tumour models." (PMID 40852716, 2025). "Decreased anti-tumor immune responses in the tumor microenvironment have been associated with the CTLA-4/CD80,CD86 axis between immune cells and tumoral cells (Derakhshani, Hashemzadeh, Asadzadeh, and Shadbad 2021)." (PMID 39905036, 2025). "Tumor-infiltrating Tregs expressed high levels of cell surface molecules associated with T-cell activation, such as CTLA4, PD-1, LAG3, TIGIT, ICOS, and TNF receptor superfamily members." (PMID 40092987, 2025). "In tumor cells, xCT promotes tumor growth, accompanied by suppression of anti-tumor immunity, and the xCT loss in tumor cells acts synergistically with the immunotherapeutic agent anti-CTLA-4." (PMID 40688069, 2025). "Upregulation of LAG-3, TIM-3, TIGIT, and VISTA has been observed in patients with tumor recurrence after anti-PD-1/L1 or anti-CTLA-4 therapy, indicating the presence of an underlying mechanism of acquired resistance." (PMID 40075727, 2025). "For instance, variants of the well-known immunosuppressive receptors PD-1 and CTLA-4, which blunt tumor immunosurveillance, correlate with the risk of developing cancer." (PMID 41469691, 2025). "For instance, certain CTLA-4 and PD-1 SNPs were associated with better survival rates or higher toxicity risks, while PD-L1 SNPs influenced tumor responses to ICIs." (PMID 41244914, 2025). "Combining the PLG scaffold DC vaccine with anti-cytotoxic T lymphocyte-associated protein 4 antibodies (CTLA-4) antibodies showed promising tumor regression and CTL activity, preventing multiple scaffold administrations." (PMID 41176596, 2025). "Conflicting mechanisms both suppressing and promoting tumor are associated with anti-CTLA-4 and explain their varied clinical results." (PMID 41045934, 2025). "Additional immunosuppressive cells, including PD-1+ B cells, Th17, Th2, tumor-associated neutrophils, fibroblasts, and CTLA-4+ dendritic cells, further exacerbate immune evasion and correlate with poor prognosis in HCC." (PMID 41012682, 2025).
tumor (continued). "Immunohistochemical analysis was planned to be performed on 50 patient samples to assess a significant association between CTLA-4 expression and tumor characteristics." (PMID 40861696, 2025). "Interventions included PD-1 monoclonal antibodies (nivolumab and pembrolizumab), cytotoxic T-lymphocyte-associated protein 4 (CTLA-4) monoclonal antibody ibritumomab, and DC vaccines, all demonstrating good anti-tumor effects." (PMID 40535136, 2025). "Both are now used widely for many other cancers and are often used as dual therapy with ipilimumab, a Cytotoxic T-Lymphocyte-Associated Protein 4 (CTLA-4) inhibitor, due to their synergistic effects in targeting tumor cells." (PMID 41041647, 2025). "Different ICIs act in different phases and sites of immune response, i.e., CTLA-4 is implicated in the priming phase within local/regional lymph nodes, while PD-1/PD-L1 works on the effector phase at tumor microenvironment level." (PMID 41009661, 2025). "By targeting immune checkpoints, including cytotoxic T-lymphocyte-associated protein 4 (CTLA-4) and programmed death-1 (PD-1)/PD-ligand 1 (PD-L1), ICIs have elicited durable responses and survival gains across multiple tumor types." (PMID 41451229, 2025). "ICIs enhance immune system eradication of tumor cells by blocking immune checkpoint proteins like PD-L1, programmed cell death protein 1 (PD-1), and cytotoxic T-lymphocyte-associated antigen-4 (CTLA-4), which act as brakes on immune cells." (PMID 40227747, 2025). "Tumor-derived VEGF, when combined with tumor-associated macrophages, can induce high expression of PD-1 and CTLA-4 on the surface of CD8+ T cells, leading to resistance to PD-1 and PD-L1 therapy." (PMID 40260303, 2025). "Once activated, it blocks CTLA-4, enhancing the anti-tumor immune response while aiming to minimize systemic side effects often associated with traditional CTLA-4 blockade." (PMID 40739089, 2025). "Elevated TIDE score usually indicates stronger immune evasion mechanisms in the tumor and poorer immunotherapy efficacy, which is associated with reduced response rate to immunotherapies such as PD-1/PD-L1 inhibitors and CTLA-4 inhibitors." (PMID 41262238, 2025). "The development of local inflammation is facilitated by the upregulation of miR-155, which results in the initiation of CTLA-4, which subsequently causes tumor invasion." (PMID 40727443, 2025). "The development of local inflammation is facilitated by the upregulation of miR-155, which results in the initiation of CTLA-4, which in turn causes tumor invasion." (PMID 40727443, 2025). "Specifically, dual PD-1 and cytotoxic T-lymphocyte-associated antigen 4 (CTLA-4) inhibition, when administered with a FasL-neutralizing antibody, results in a significantly greater reduction in tumor burden than checkpoint blockade alone." (PMID 41163091, 2025). "ICIs trigger an anti-tumor immune response by targeting inhibitory pathways in T-cells, including Cytotoxic T-Lymphocyte-Associated Protein 4 (CTLA-4), Programmed Cell Death Protein-1 (PD-1), and its ligand PD-L1." (PMID 40458297, 2025). "Whereas, once the tumor turns aggressive, tumor cells express immune checkpoint modulators [such as cytotoxic T lymphocyte-associated protein 4 (CTLA-4) and programmed cell death 1 ligand 1 (PD-L1)] to suppress the immune response." (PMID 39966355, 2025). "T cell exhaustion, a dysfunctional state marked by TOX-driven transcriptional reprogramming and sustained expression of inhibitory receptors (e.g., LAG-3, CTLA-4), is a hallmark of chronic viral infections and tumor microenvironments." (PMID 40830893, 2025). "Tumor cells can express inhibitory ligands such as cytotoxic T-lymphocyte-associated protein 4 (CTLA-4) and programmed cell death ligand 1 (PD-L1), which send “stop” signals to active T cells, enabling the tumor to escape cell-mediated immunity." (PMID 40547026, 2025).
tumor (continued). "Additional biomarkers (e.g., CTLA-4, PD-L1 combined positive score, tumor mutational burden, and measures of tumor-infiltrating lymphocytes) are increasingly used to guide ICI eligibility or to stratify risk." (PMID 41374963, 2025). "Traditionally, CTLA4 has been associated with T-cell dysfunction and the suppression of anti-tumor immunity." (PMID 40005446, 2025). "ICB targeting programmed cell death-1 (PD-1), its ligand (PD-L1), or cytotoxic T-lymphocyte-associated antigen 4 (CTLA-4) has shown durable anti-tumor effects in various cancers." (PMID 40519901, 2025). "It was confirmed that tumor cells can release exosomes carrying PD-1, PD-L1, and cytotoxic T-lymphocyte-associated antigen 4 (CTLA-4)." (PMID 39852160, 2025). "Programmed cell death ligand 1 (PD-L1) overexpression on tumor/stromal cells engages programmed death receptor 1 (PD-1) to exhaust T cells, while cytotoxic T lymphocyte associate protein-4 (CTLA-4) competitively blocks CD28 co-stimulation." (PMID 41409273, 2025). "Tumor-associated eosinophils (TAEs) showed an 85% sensitivity to anti-CTLA4 therapy in EO771 tumors." (PMID 40281554, 2025). "ICIs work principally by overcoming immune tolerance against the tumor, mediated by inhibitory molecules such as PD-1, PD-L1, or cytotoxic T-lymphocyte-associated protein 4 (CTLA-4), and enhancing the body's own immune response." (PMID 41426882, 2025). "Cytotoxic T-lymphocyte associated protein 4 (CTLA-4) plays a key role in tumor immune reactions with PD-1." (PMID 40895574, 2025). "Dysfunction in tumor-infiltrating DCs is caused by immune or leukemic cells that express PD-L1, PD-1, CTLA4, and TIM3." (PMID 39994019, 2025). "Immune checkpoints, such as programmed cell death protein 1 (PD-1) and cytotoxic T lymphocyte-associated protein 4 (CTLA-4), are critical regulators of the immune system, controlling its ability to recognize and eliminate tumor cells." (PMID 40104501, 2025). "Applying ICIs, especially monoclonal antibodies targeting PD-1, PD-L1, and cytotoxic T-lymphocyte-associated protein 4 (CTLA-4), and modulating immune checkpoints on tumor cells, bring significant breakthroughs in treating solid tumors, including HCC." (PMID 38388484, 2024). "Cytotoxic T lymphocyte Ag‐4 (CTLA‐4) and PD‐1 are important coinhibitory molecules that cause T lymphocyte dysfunction, ultimately promoting tumor cell evasion of host immune clearance." (PMID 38525112, 2024). "Ctla4 induces Pdcd4 in cytotoxic T cells, and Pdcd4 deficiency enhances their anti-tumor effector functions." (PMID 38645169, 2024). "-associated antigen-4 (CTLA-4) pathways interacting with inhibitory antibodies to enable activated T cells to release cytokines, perforins, granzymes, etc., to kill tumor cells in a rapidly evolving immunotherapeutic regimen." (PMID 39165682, 2024). "combined an OV vector encoding anti‐PD‐L1 with anti‐CTLA‐4 in a mouse tumor model, achieving better tumor suppression than monotherapy." (PMID 39399642, 2024). "In contrast, gene Ctla4 encoding CTLA4 checkpoint was only modestly upregulated in several tumor samples." (PMID 39737979, 2024). "CTLA-4, which is commonly expressed on Tregs to downregulate T cell-mediated responses and is stimulated by tumour cells to cause T cell exhaustion." (PMID 38474047, 2024). "The function of immunosuppressive checkpoints in T cells, including programmed cell death protein (PD-1) and cytotoxic T lymphocyte (CTL)-associated protein 4 (CTLA-4), provides a basis for tumor immunotherapy." (PMID 38415258, 2024). "In this study, only leukocytes count and tumor stage that were significantly associated with CTLA-4 expression with p-values 0.004 and 0.020, respectively." (PMID 38978137, 2024). "Cancer cells often evade anti-tumor immune responses by upregulating inhibitory molecules such as cytotoxic T lymphocyte-associated antigen-4 (CTLA4) and programmed death-1 (PD-1)/programmed death-ligand 1 (PD-L1), as well as suppressive cytokines." (PMID 38760774, 2024).